INS (insulin)
Diseases named in the same sentence as INS in open-access papers (continued):
Sharing a sentence is not in itself a finding about the gene and the disease.
Insulin resistance (continued). "Insulin resistance increased the concentrations of TG and HDL-C, and in turn, the AIP might affect insulin secretion, β-cell dysfunction, and cause poor glycemic control in type 2 diabetes patients." (PMID 28549070, 2017). "Insulin resistance means that insulin-sensitive tissues, such as the liver, muscles, and adipose tissues, exhibit a lower biological effect when stimulated with the normal serum concentration of insulin." (PMID 28928791, 2017). "In addition, the total effect of the association between BMI or WC and BP was found to be mainly mediated by insulin/insulin resistance, which is further explained by TG, TC and FG." (PMID 28710353, 2017). "Taking into consideration that insulin signalling and glucose metabolism correlate positively with bone turnover and bone formation, a logical question arises as to whether bone develops insulin resistance and, if so, how it is manifested." (PMID 28434032, 2017). "The association between breast cancer (BCa) presence and altered glucose/insulin metabolism is controversial likely due to an inaccurate insulin resistance (IR) assessment and inappropriate stratification of patients by body-mass index (BMI) and menopausal state." (PMID 29113405, 2017). "However, increased insulin resistance combined with an inability to secrete the additional insulin required to maintain glucose homeostasis can result in the development of gestational diabetes mellitus (GDM) in the mother and macrosomia in the baby." (PMID 28475161, 2017). "Finally, a study in C2C12 myotubes revealed that miRNA-106b expression was increased upon palmitic acid-induced insulin resistance while silencing of miRNA-106b improved mitochondrial health and promoted insulin sensitivity." (PMID 28983252, 2017). "Transcriptomic profiles showed that the HCBD had a strong impact on the expression of genes involved in the NAFLD and insulin signaling pathways, which may lead to the development of insulin resistance in hepatocytes and eventually NAFLD." (PMID 29121861, 2017). "Previous studies have shown that activation of the RAS may impair insulin signalling, contributing to insulin resistance, which is a key pathophysiological mechanism in NAFLD." (PMID 28419124, 2017). "Current treatments for T2D are focused on improving insulin resistance and insulin secretion." (PMID 29018279, 2017). "Furthermore, SF suppresses the excessive secretion of insulin in response to HG stimulation, thereby reducing obesity and insulin resistance." (PMID 28977868, 2017). "Most monogenic insulin resistance is caused not by direct perturbation of cell autonomous insulin signalling, but by defects in adipocyte differentiation or function." (PMID 29242557, 2017). "An increase in TG in blood can be caused by insulin resistance; however, the insulin sensitivity indexes did not indicate a significantly greater insulin resistance in goats receiving Strep." (PMID 28740504, 2017). "It is characterized by hyperglycaemia due to insulin resistance and decreased insulin activity." (PMID 28761062, 2017). "In this work, the levels of C-peptide as well insulin increased in patients with OW and obesity, indicating an elevated production of insulin that might be related to the insulin resistance generally observed in diabetic patients." (PMID 28425473, 2017). "The pre-gestational diabetic pregnant women had significantly higher plasma glucose, insulin and insulin resistance than the non diabetic pregnant women.The plasma glucose and insulin resistance in the non diabetic pregnant women were significantly low probably due to the early stage of pregnancy." (PMID 28732072, 2017). "The higher glycaemia measured in P2X7−/− mice despite elevated serum insulin concentrations could be a sign of insulin resistance." (PMID 29018292, 2017). "Consequently, peripheral insulin resistance arises the brain insulin signaling impairment that was described in obese insulin resistance rats." (PMID 28505155, 2017).
Insulin resistance (continued). "Although the sequence and interrelationship of biological events in the pancreas and skeletal muscle remain to be elucidated, SeP may disrupt glucose homoeostasis, not only by increasing insulin resistance, but also by impairing insulin secretion." (PMID 29162828, 2017). "In addition, over-expression of RNase-L in mouse and human myotubes were demonstrated to improve insulin signaling in a palmitate-induced insulin resistance model." (PMID 28399925, 2017). "In light of UcOC's ability to improve insulin secretion by β-cells and the age-related decline in pancreatic function, we investigated the effect of our interventions on the DI, a measurement of insulin secretion that expresses the ability of the β-cells to adequately respond to insulin resistance." (PMID 28951766, 2017). "Already at the early stages of the disease, there were initial metabolic deregulations, evidenced by alterations in glucose tolerance during the GTT and ITT, as well as the glucose and insulin levels, indicative of insulin resistance, in agreement with other studies." (PMID 28635632, 2017). "The proportion of insulin resistance versus beta cell dysfunction (insulin secretion) differs among individuals, with some having primarily insulin resistance and only a minor defect in insulin secretion; whereas, others have slight insulin resistance and primarily a lack of insulin secretion." (PMID 28070499, 2017). "Moreover, we previously showed that the PGR complex is useful in improving BMI, metabolic parameters and glucose-insulin metabolism in obese children and adolescents with severe hyperinsulinism and insulin resistance." (PMID 28531113, 2017). "Studies on elevated fasting insulin or insulin resistance (IR) and cardiovascularor all-cause mortality risk in non-diabetic individuals have yielded conflictingresults." (PMID 28811358, 2017). "However, no large prospective studies have simultaneously evaluated several acute-phase proteins (e.g., GlycA, IL-1RA, and hs-CRP) as predictors for changes in insulin secretion, insulin resistance, and insulin resistance-related traits." (PMID 28911155, 2017). "Insulin resistance may occur also in the brain and results in reduced central insulin signaling, altering a variety of insulin mediated events of importance for memory functions." (PMID 29141041, 2017). "In the present study, we discovered that TNF-α might stimulate PA transcytosis across cardiac microvascular endothelial cells, which further impaired the insulin-stimulated glucose uptake by cardiomyocytes and promoted insulin resistance." (PMID 28304381, 2017). "Moreover, increased insulin secretion is in part related to pancreatic islet hyperplasia with progression of insulin-resistance by HFD supply." (PMID 28867797, 2017). "Previous findings have suggested the GC effects on insulin sensitivity are tissuespecific, such that they might induce insulin resistance in muscle but increase insulinsensitivity in subcutaneous adipose tissue in vivo." (PMID 28323916, 2017). "Furthermore, significant differences were found in insulin sensitivity (p = 0.003), and insulin resistance (p = 0.001) indices between the two groups." (PMID 29299442, 2017). "Novel translational findings from our laboratory now afford a fresh perspective on how caloric excess may contribute to the deterioration of insulin action, perhaps early in the development of insulin resistance." (PMID 28811359, 2017). "Previous studies have shown that a direct renin inhibitor increased pancreatic islet function and upregulated insulin action on skeletal muscle glucose transport, further improving glucose intolerance and insulin resistance through the downregulation of tissue Ang II and Ang II type 1 receptor." (PMID 28700686, 2017). "Recently, a growing body of evidence indicates that LncRNAs may act as a link between insulin signalling and insulin resistance." (PMID 29050364, 2017).
Insulin resistance (continued). "Whether the feedback occurs in the insulin-targeted tissues (i.e., fat, liver, and skeletal muscle) and becomes stable to result in insulin resistance depends on sustained local activation of IKK." (PMID 28912810, 2017). "In DM patients, insulin resistance leads to a compensatory increase in insulin secretion, and by inhibition of IGF binding proteins, this hyperinsulinemia may increase the biological activity of IGF-1, which is an antiapoptotic and mitogenic factor." (PMID 28423026, 2017). "Indeed, proteins secreted by the duodenum and jejunum from both diabetic mice and insulin resistant humans induce insulin resistance in both normal mice and in muscle cells by stimulating the mTORC2 pathway [18•]." (PMID 28185153, 2017). "Intriguingly, fastingblood glucose and insulin as well as Homeostasis model assessment of insulin resistance (HOMA-IR) levels were lower in Hmox1fl/flPdgfraCre as compared to Hmox1fl/fl control mice, indicating improved metabolic health in the HFD-treated Hmox1fl/flPdgfraCre mice." (PMID 28102348, 2017). "It has been demonstrated that immune cells such as macrophages reside in or infiltrate metabolic organs under obese conditions and cause the so-called low-grade inflammation or metaflammation that impairs insulin action thus leading to the development of insulin resistance." (PMID 28233125, 2017). "Obesity development could lead to insulin resistance, characterized by the raised level of circulating insulin, as well as suppressed insulin sensitivity." (PMID 28212343, 2017). "We hypothesized that CLW would have a hypoglycemic effect by reducing insulin resistance and tightly regulating insulin secretion in an Asian type 2 diabetic animal model." (PMID 29104217, 2017). "IFG and IGT are two different states in insulin secretion and insulin resistance." (PMID 28531120, 2017). "Adiponectin is an insulin sensitizer with anti-insulin resistance and anti-inflammatory properties." (PMID 28208663, 2017). "As mechanistic target of rapamycin (mTOR) is activated by insulin signalling, and may also regulate autophagy, we also investigated whether mTOR signalling had any involvement in insulin-induced insulin resistance in podocytes." (PMID 28852804, 2017). "More interestingly, our data showed that increasing the MCFA ratio not only reduced HFD-induced systemic and adipose insulin resistance but also rescued hepatic insulin sensitivity by downregulating basal Akt phosphorylation and enhancing insulin-stimulated Akt phosphorylation." (PMID 29070903, 2017). "Moreover, apoA-I has been documented to independently promote insulin secretion and glucose uptake and to be negatively correlated with insulin resistance in patients with type 2 diabetes." (PMID 28372564, 2017). "Pregnancy is typically accompanied by physiological insulin resistance that begins the second trimester and progresses through the third trimester, leading to an increase in maternal insulin secretion to maintain blood glucose levels as a consequence of adaptive pancreatic β-cell proliferation." (PMID 28081192, 2017). "However, there are few studies on the relationship between AGEs and insulin secretion ability or insulin resistance in patients with type 2 diabetes." (PMID 28695132, 2017). "Skeletal muscle insulin resistance, in terms of dysfunction of cellular mechanisms to respond appropriately to insulin, and the resulting reduction of peripheral glucose uptake seem to develop early, as shown by studies in young lean individuals with muscle-specific insulin resistance." (PMID 29286343, 2017). "Since we found significantly lower fasting insulin levels in rats treated with sulodexide, this agent may affect the early stage of insulin resistance in high fat diet." (PMID 28399917, 2017).
Insulin resistance (continued). "Activation of PPARγ by TZD leads to increase the storage capacity of fatty acids in the adipocytes and thereby to decrease the amount of circulating fatty acids and ameliorate the insulin resistance, which finally leads to the reduced plasma insulin and glucose levels." (PMID 28690544, 2017). "Metformin, a biguanide agent that decreases hepatic glucose production and increases peripheral insulin sensitivity, has been used in conjunction with a lifestyle intervention program in T2DM obese adolescents with clinical insulin resistance to achieve weight loss and improve insulin sensitivity." (PMID 28531113, 2017). "VitD status can interfere with insulin secretion and insulin resistance." (PMID 29149839, 2017). "These animal studies suggest that bone is a site of insulin resistance, and the interruption of osteoblastic insulin signaling in insulin-resistant subjects may lead to a reduction in bone mass." (PMID 28704413, 2017). "In addition to the influence of NAMPT on lipid metabolism, we also found that FK866 markedly reduced Akt phosphorylation, indicating that NAMPT also improve insulin resistance in NAFLD through promoting insulin signaling in hepatocytes." (PMID 28449683, 2017). "Furthermore, we investigated fasting glucose and have no data on other potentially relevant markers of glucose metabolism and insulin resistance, such as baseline insulin and insulin-like growth factor-I." (PMID 29383194, 2017). "Interestingly, hepatic insulin resistance by alcohol was due to impaired hypothalamic insulin action to suppress hepatic glucose production." (PMID 28067302, 2017). "Insulin resistance is a condition in which a given concentration of insulin produces a less than expected effect on target cells, and this may lead to impaired glucose tolerance ahead of overt type II diabetes mellitus." (PMID 29081894, 2017). "Thus, increased TLR4-driven signalling in muscle from insulin-resistant obese and/or type 2 diabetic subjects contributes to worsening insulin-resistance and inflammation." (PMID 28240307, 2017). "Therapeutic strategies targeting PKR1 could be important to treat obesity and obesity-associated insulin resistance, since PKR1 signaling suppresses appetite, reduces adipocyte expansion, promotes normal fat storage, and increases insulin sensitivity." (PMID 28447033, 2017). "The protective effects of fatty fish consumption on the progression of insulin resistance were tested in combination with other products with recognized effect on glucose metabolism (whole grain and low postprandial insulin response grain products, and bilberries) in a clinical trial." (PMID 28820493, 2017). "Therefore, the disruption of insulin levels, insulin signalling, or insulin resistance in the brain can lead to the dysfunction and degeneration of neurons." (PMID 28770024, 2017). "Metabolism-controlling stress hormones, especially GCs and NE could exert anti-insulin effects, and in the long run induce insulin resistance." (PMID 28676747, 2017). "The AMPK signaling pathway could contribute to correction of insulin resistance through bypassing the insulin-regulated system for GLUT4 translocation." (PMID 28642704, 2017). "Severe hepatic insulin resistance was characterized using the hyperinsulinemic-euglycemic clamp technique and was attributed to increased hepatic diacylglycerol content and protein kinase C-epsilon activation and decreased insulin activation of Akt2." (PMID 28163820, 2017). "Metformin, which is a drug used for treatment of insulin resistance, but does not increase the insulin concentration in blood, reduced the risk of pancreatic cancer by 62%, particularly when metformin treatment was continued for five years or longer." (PMID 28417915, 2017). "Greater change in FVC was related to high insulin levels and a high insulin resistance index." (PMID 28346522, 2017).
Insulin resistance (continued). "Accumulating evidence has shown that the impaired insulin signaling pathway, together with inflammatory responses, promotes hepatic lipid biosynthesis and steatosis, which in turn contribute to chronic hepatic inflammation and insulin resistance." (PMID 28736524, 2017). "Reinforcing the role of JNK in the development of hypothalamic insulin resistance in HFD fed rodents, mice with JNK1 deficiency in the brain exhibit improved insulin sensitivity in both central and peripheral tissues, preventing adipose tissue dysfunction and hepatic steatosis under HFD feeding." (PMID 28677618, 2017). "The latest study suggests that W. somnifera normalizes fructose-induced hyperglycemia in rats by reducing the increases of blood glucose, insulin, homeostasis model assessment for insulin resistance, IL-6 and TNF-α, thus alleviating inflammation and improving insulin sensitivity." (PMID 28146130, 2017). "Moreover, MANF triggers hypothalamic insulin resistance by enhancing the ER localization and activity of PIP4k2b, a kinase known to regulate insulin signaling." (PMID 28924165, 2017). "We evaluated the presence of insulin secretory dysfunction and insulin resistance before the initiation of CST in 13 patients with new-onset DM, but could not in patients with pre-existing DM because of the influence of diabetic medication." (PMID 29166415, 2017). "Furthermore, it has been suggested that lactate-induced insulin resistance is related to compromised insulin signaling and reduced insulin-triggered glucose transport in skeletal muscle." (PMID 28077918, 2016). "Insulin resistance was assessed using an insulin tolerance test (ITT)." (PMID 27261415, 2016). "TReg cells in WAT improve insulin sensitivity in an IL-10-dependent fashion and may regulate insulin resistance by modulating the gut microbiome." (PMID 27727191, 2016). "HOMA-IR is a surrogate measure of insulin resistance that has been shown to be more strongly associated with cardiovascular disease than glucose or insulin concentrations alone in non-diabetic patients." (PMID 26892461, 2016). "The previous study suggested that although fructose does not appear to acutely increase insulin levels, chronic exposure seems to indirectly cause insulin resistance and obesity through other mechanisms, such as GLUT5 fructose transporters and inflammation." (PMID 28035952, 2016). "Islet physiology is finely modulated by a myriad of factors, including vitamin D. Vitamin D deficiency, referred to clinically as hypovitaminosis D, impairs insulin secretion and increases insulin resistance, key features of T2DM and related metabolic diseases." (PMID 26959059, 2016). "Obviously, enhanced oxidative stress may result in insulin resistance and influence on insulin secretion in patients with depressive disorder." (PMID 27683078, 2016). "Accordingly, the insulin resistance biomarkers such as serum insulin, leptin, adiponectin, retinol binding protein 4 (RBP4) and lipid profile were assayed, and the underlying transcriptomic changes induced by C.nutans on hepatic insulin resistance-related genes were evaluated." (PMID 26924713, 2016). "In addition, p50α/p55α knockout mice exhibit improved insulin sensitivity, lower fat masses and protection against obesity-induced insulin resistance." (PMID 27795741, 2016). "Since insulin resistance was first recognised several decades ago, a number of ideas have been put forward to try and explain the link between excess adiposity and reduced tissue sensitivity to insulin." (PMID 26661101, 2016). "For example overexpressed ERK impairs insulin signaling and induces insulin resistance." (PMID 26930065, 2016). "However, in T2D, where insulin resistance and high circulating levels of endogenous insulin are key concepts, the role of exogenous insulin is unclear." (PMID 27391319, 2016).